NTN1 (netrin 1)
Diseases named in the same sentence as NTN1 in open-access papers (continued):
Sharing a sentence is not in itself a finding about the gene and the disease.
retinoblastoma (2 papers, 2021 to 2024). A malignant tumor that originates in the nuclear layer of the retina. "Blocking Netrin-1 also ameliorated YAP-induced cytostasis in WERI-RB1 retinoblastoma cells." (PMID 39172021, 2024). "Netrin-1 showed a high expression in retinoblastoma, which could confirm its carcinogenic role." (PMID 34646884, 2021). "Examination of RNA-Seq data from retinoblastoma and SCLC revealed up-regulation of multiple UNC5 and NTN members following forced YAP expression, including UNC5B/C/D and NTN1, but not NTN3." (PMID 39172021, 2024).
rheumatoid arthritis (2 papers, 2021 to 2024). A chronic, systemic autoimmune disorder characterized by inflammation in the synovial membranes and articular surfaces. "Regarding the interaction between netrin-1 and DCC or UNC5 in bone disorders, netrin-1 is highly expressed in the synovial fluid of rheumatoid arthritis patients, and activation of the netrin-1/UNC5B axis has been shown to prevent bone destruction." (PMID 38628640, 2024).
scleroderma (2 papers, 2023 to 2025). Scleroderma is a rare autoimmune connective tissue disorder characterized by abnormal hardening of the skin and, sometimes, other organs. "ADSCs may promote angiogenesis and especially lymphangiogenesis via VEGFD, MMP2, and Netrin 1, leading to revascularisation and normalisation of the disturbed microvascular architecture found in scleroderma." (PMID 37443817, 2023). "They identified NTN1, VEGFD, MMP2, FGF2, and FNDC5 as potential players in how the ADSCs secretome may disrupt vascular and perivascular inflammation hubs in scleroderma and thereby promote angiogenesis and lymphangiogenesis." (PMID 40584563, 2025). "The few effector molecules that were identified, including NTN1, VEGFD, MMP2, FGF2, and FNDC5, provide evidence for the anti-fibrotic and anti-inflammatory effects of the ADSC secretome; however, these few factors cannot explain all observed effects on scleroderma skin after autologous fat grafting." (PMID 37443817, 2023).
thymoma (2 papers, 2020 to 2025). A neoplasm arising from the epithelial cells of the thymus. "The transcription of NTN1 in THYM is negatively regulated by EZH2 (r = −0.4056), suggesting that the low expression of NTN1 in thymoma is related to the occurrence and development of THYM." (PMID 32251318, 2020). "Of these, NEO1 has the strongest correlation (r = − 0.5814), suggesting that EZH2 may alter the expression of NTN1, NEO1, and UNCB-D to promote the occurrence of thymoma." (PMID 41407823, 2025). "Moreover, EZH2 negatively regulates NTN1, NEO1, and UNCB-D in thymoma." (PMID 41407823, 2025).
acute lymphocytic leukemia (1 paper, 2021). "The pre-B acute lymphocytic leukemia cell lines 697 and RCH-ACV did not respond to BMP4 treatment with increased pSMAD1/5 levels and thus could not be evaluated for possible inhibition by netrin-1." (PMID 33883596, 2021).
Alport syndrome (1 paper, 2025). A rare renal disease characterized by glomerular nephropathy with hematuria progressing to end-stage renal disease (ESRD), frequently associated with sensorineural deafness, and occasionally with ocular anomalies. "A Study on Netrin-1 and Cyclophilin A (CypA) as inflammatory biomarkers for renal injury and Alport syndrome was the first to highlight these crucial biomarkers’ role." (PMID 39856623, 2025).
anxiety disorder (1 paper, 2022). A category of psychiatric disorders which are characterized by anxious feelings or fear often accompanied by physical symptoms associated with anxiety. "These novel findings suggest that long-lasting over-expression of Netrin-1 can mediate visceral hypersensitivity and anxiety disorder from the post-weaning period to adulthood by activating DCC/GluA1 pathway in the hippocampus." (PMID 35966013, 2022). "Early intervention targeting Netrin-1 in the hippocampus was effective in the treatment of comorbid visceral hypersensitivity and anxiety disorder." (PMID 35966013, 2022). "Moreover, the results suggested that Netrin-1/DCC/GluA1 signaling pathway may be a potential therapeutic target for the treatment of visceral hypersensitivity and associated anxiety disorder." (PMID 35966013, 2022). "Using a combination of RNA-Seq, behavioral tests, lentivirus interference, and molecular biology techniques, we found that over-expression of Netrin-1 could induce visceral hypersensitivity and anxiety disorder in different life periods through activating DCC/GluA1 pathway in the hippocampus." (PMID 35966013, 2022).
B-cell lymphomas (1 paper, 2022). "This difference of netrin-1 cytoplasmic expression between low- and high-grade B-cell lymphomas was significant (p< 0.001)." (PMID 36136711, 2022).
bladder pain syndrome (1 paper, 2022). "This study aimed to combine plasma netrin-1 and clinical parameters to construct a diagnostic model for bladder pain syndrome/interstitial cystitis (BPS/IC)." (PMID 34897588, 2022).
cardiac hypertrophy (1 paper, 2025). "Netrin-1 has been shown to prevent MI caused by ischemia-reperfusion and to suppress the development of cardiac hypertrophy and heart failure induced by transverse aortic constriction." (PMID 41531492, 2025). "Furthermore, PGE1 has been found to mitigate angiotensin II (AngII)-induced cardiac hypertrophy by activating of the EP3 receptor, which upregulates Netrin-1 and inhibits the downstream MAPK signaling pathway." (PMID 41531492, 2025).
cerebral infarction (1 paper, 2021). An ischemic condition of the brain, producing a persistent focal neurological deficit in the area of distribution of the cerebral arteries. "When dexmedetomidine was combined with Netrin-1, the cerebral infarction volume was further reduced (P < 0.01)." (PMID 33584197, 2021).
cerebrovascular diseases (1 paper, 2020). "This work links cellular senescence to elevated SNA in aged tissues by the bridge of netrin-1, which contributes to SNS hyperactivity-induced aging-related pathologies, such as Cardiovascular and cerebrovascular diseases, OA, fatty liver, and brain cognitive function." (PMID 33390926, 2020).
CHARGE syndrome (1 paper, 2019). CHARGE syndrome is a multiple congenital anomaly syndrome characterized by the variable combination of multiple anomalies, mainly Coloboma; Choanal atresia/stenosis; Cranial nerve dysfunction; Characteristic ear anomalies (known as the major 4 C's). "Mice lacking Chd7 display CHARGE syndrome-like phenotypes and exhibit abnormal expression of Ntn1." (PMID 31162046, 2019).
chondrosarcoma (1 paper, 2023). A malignant cartilaginous matrix-producing mesenchymal neoplasm arising from the bone and soft tissue. "Our observations showed that the suppression of NTN1 not only reduced the proliferation and migration of osteosarcoma, chondrosarcoma, and antler cartilage cells but also downregulated the expression of oncogenic cyclin D1 in these cells." (PMID 37446017, 2023). "To assess whether miR-PC-2869 exerts inhibitory effects on chondrosarcoma cells by downregulating CDK8, EEF1A1, and NTN1, we employed RNA interference to individually knock down the expression of each gene in SW1353 cells." (PMID 37446017, 2023).
Chorioretinal coloboma (1 paper, 2025). Absence of a region of the retina, retinal pigment epithelium, and choroid. "In conclusion, we report a novel NTN1 variant likely causing chorioretinal coloboma, SNHL and polydactyly in our patient." (PMID 39648562, 2025). "This variant may impair the adhesive properties of NTN1 in the optic fissure, preventing fusion and resulting in the chorioretinal coloboma observed in this patient." (PMID 39648562, 2025). "A novel heterozygous de novo NTN1 missense variant was identified in a patient with chorioretinal coloboma, sensorineural deafness and polydactyly, through screening of micropthalmia anophthalmia coloboma (MAC) patients in the Genomics England 100 000 Genomes Project dataset." (PMID 39648562, 2025).
choroidal neovascularization (1 paper, 2025). An eye disorder described by the growth of new blood vessels that originate from the choroid through a break in the Bruch membrane into the sub–retinal pigment epithelium (sub-RPE) or subretinal space. "In pathological settings, NTN1 overexpression reinforced BRB integrity in oxygen-induced retinopathy (OIR), improving electroretinogram (ERG) amplitudes and rescued vascular leak in laser-induced choroidal neovascularization (CNV)." (PMID 41196411, 2025).
Chronic constipation (1 paper, 2024). Constipation for longer than three months with fewer than 3 bowel movements per week, straining, lumpy or hard stools, and a sensation of anorectal obstruction or incomplete defecation. "Previous studies suggest a potential link between reduced NTN‐1 levels and the severity of chronic constipation in PD patients." (PMID 39215401, 2024). "Future investigations using rigorous methodologies are crucial to unravel the complex relationship between plasma NTN‐1 levels and peripheral nonmotor symptoms, particularly chronic constipation." (PMID 39215401, 2024).
chronic periodontitis (1 paper, 2022). A chronic inflammatory process that affects the tissues that surround and support the teeth. "This study was designed to assess gingival crevicular fluid (GCF) netrin-1 levels in chronic periodontitis to test its validity as an inflammatory marker in periodontal disease." (PMID 35919444, 2022). "In contrast to our results, Gunpinar et al22 reported higher GCF netrin-1 levels in chronic periodontitis patients than in healthy individuals." (PMID 35919444, 2022). "Netrin-1 may have a significant role in the inflammatory process of chronic periodontitis; thus, it could be a promising anti-inflammatory marker in periodontal disease." (PMID 35919444, 2022).
colon adenoma (1 paper, 2020). An adenoma that arises from the colon. "Furthermore, it was found that the netrin-1 protein level also increased dramatically in naturally aging mice tissues and human colon adenoma tissues in comparison to young mice tissues and human non-lesion colon tissues respectively." (PMID 33390926, 2020).
colorectal adenocarcinoma (1 paper, 2023). The most common type of colorectal carcinoma. "Furthermore, both NTN-1 and ACM were found to increase NEO1 and DCC mRNA levels in two colorectal adenocarcinoma cell lines, together with UNC5B downregulation in HT-29 cells when stimulated with ACM." (PMID 36831381, 2023).
congenital nephrotic syndrome (1 paper, 2016). "MBP enables the production, secretion, and purification of netrin-1 subdomains, intracellular as well as transmembrane proteins and mutant ECM proteins, such as the congenital nephrotic syndrome causing laminin β2 R246Q mutated chain." (PMID 27029048, 2016).
deafness (1 paper, 2025). An inherited or acquired condition characterized by the complete loss of the ability to hear from one or both ears. "In human patients, KCNN3 and NTN1 have both been implicated in conditions related to hair growth, including onychodystrophy syndromes and deafness." (PMID 40725390, 2025).
Down syndrome (1 paper, 2023). "Indeed, SMOC1 and NTN1 were recently identified among the most highly-enriched proteins in amyloid plaques in early-onset AD and individuals with Down syndrome and AD41." (PMID 37414805, 2023).
dyslipidemia (1 paper, 2021). "Moreover, circulating Netrin-1 was inversely associated with the presence of dyslipidemia (p < 0.05)." (PMID 33567662, 2021).
endometrial tumours (1 paper, 2023). "We analysed netrin-1 expression by quantitative PCR with reverse transcription (RT–qPCR) in a cohort of 72 human endometrial tumours." (PMID 37532934, 2023). "Netrin-1 (and UNC5B) positivity was monitored in most endometrial tumours by immunohistochemistry (IHC)." (PMID 37532934, 2023).
fetal growth restriction (1 paper, 2024). A fetus that does not grow beyond the 10th percentile of conventionally accepted weight for gestational age. "Of these, NTN1 (Netrin1) is of particular interest as it is reduced in the placentas of women with fetal growth restriction and potentially influences placental size by increasing the viability of placental microvascular endothelial cells." (PMID 38813868, 2024).
galactosemia (1 paper, 2020). "Contrasting with hepatic cells, no alterations of N-glycoprofiles in MIG (metabolic induction of galactosemia)-HEK293 cells were revealed for an inducible secretory netrin-1 probe by MALDI-MS." (PMID 32138379, 2020).
geographic atrophy (1 paper, 2015). "Similar results existed for neovascular (NV) AMD and geographic atrophy (GA), although NTN1- and DCC-resident NV AMD-associated SNPs were not co-inherited at high frequency (r2> 0.80) with those of respective GA-associated SNPs." (PMID 25950802, 2015).
gingival fibromatosis (1 paper, 2021). "The in vivo overexpression of Netrin-1 and COL6A as well as the nuclear accumulation of p-Smad-3 indeed supported the idea that aberrant TGFβ signaling may contribute in the pathogenesis of ERS gingival fibromatosis." (PMID 34777248, 2021).
Glomerular sclerosis (1 paper, 2016). Accumulation of scar tissue within the glomerulus. "Netrin-1 also suppressed AKI-induced tubular atrophy, interstitial fibrosis, vascular dropout, and glomerular sclerosis through suppression of STAT3 and JNK signaling and IL-6 expression in tubular epithelial cells." (PMID 27176224, 2016).
hematoma (1 paper, 2017). A hematoma is a collection of blood from a vascular structure into an extravascular space. "Protein levels of netrin-1 in the peri-hematoma cortex increased by a factor of 1.7 in the ICH (48 h) group compared with the sham group." (PMID 29375318, 2017). "In addition, immunofluorescence staining further showed an increase in protein levels of netrin-1 in neurons in the peri-hematoma cortex." (PMID 29375318, 2017). "FJB staining was performed to evaluate neuronal degeneration and showed that netrin-1 administration significantly reduced the number of FJB-positive cells in both the cortex and peri-hematoma regions of ICH rats." (PMID 29375318, 2017).
Hyperinsulinemia (1 paper, 2016). An increased concentration of insulin in the blood. "Therefore, we believe that the increased netrin-1 in our patients probably was a reflection of the complications of hyperinsulinemia-induced tubular changes." (PMID 27087488, 2016).
hypertrichosis (1 paper, 2025). Excessive hair growth anywhere on the body. "Variants within KCNN3 have been associated with Zimmermann–Laband syndrome, which can be characterized by many phenotypes, including hypertrichosis, and NTN1 has roles in cochlear hair cell survival." (PMID 40725390, 2025).
immune thrombocytopenic purpura (1 paper, 2023). "The serum netrin-1 expression level in patients with AML and nonhematological malignant diseases (immune thrombocytopenic purpura, IPT; iron-deficiency anemia, IDA, etc., control group) were detected using enzyme-linked immunosorbent assay (ELISA)." (PMID 37038247, 2023).
Impaired glucose tolerance (1 paper, 2022). An abnormal resistance to glucose, i.e., a reduction in the ability to maintain glucose levels in the blood stream within normal limits following oral or intravenous administration of glucose. "Reportedly, patients with impaired glucose tolerance and T2D exhibited higher circulating levels of NTN-1 being also positively correlated with IR." (PMID 36297056, 2022).
influenza (1 paper, 2017). An acute viral infection of the respiratory tract, occurring in isolated cases, in epidemics, or in pandemics; it is caused by serologically different strains of viruses (influenzaviruses) designated A, B, and C, has a 3-day incubation period, and usually lasts for 3 to 10 days. "The TXA2-pathway does not appear to be involved in netrin-1 regulation, inasmuch as modulation of netrin-1, both in subjects receiving influenza immunisation and in those receiving high-dose aspirin for 28 days, was not related to changes in serum TXB2." (PMID 29156815, 2017).
lentivirus infection (1 paper, 2017). Virus diseases caused by the Lentivirus genus. "Netrin-1 expression was reduced by 70% by shRNA delivered via lentivirus infection." (PMID 28710382, 2017).
leprosy (1 paper, 2022). Leprosy is a chronic infectious disease affecting primarily the skin and peripheral nervous system. "We also described a molecular signature associated with neural damage in early stages of pure neural leprosy from patients (i.e., HLA-DRB1, MAPK14, GAP43, FABP7, NTN1, and LRRTM4)." (PMID 35492305, 2022).
Leukoencephalopathy (1 paper, 2025). This term describes abnormality of the white matter of the cerebrum resulting from damage to the myelin sheaths of nerve cells. "Several genome-wide association studies (GWAS) have identified single-nucleotide polymorphisms (SNPs) in the following genes: TRIO, PRKG1, ANK1, COL4A2, NTN1, and ASTN2 that were associated with increased risk of MTX-induced neurotoxicity and leukoencephalopathy on imaging in patients with ALL." (PMID 41029358, 2025).
limb ischemia (1 paper, 2018). A ischemia that involves the limb. "The study measured the plasma and tissue levels of VEGF and confirmed the upregulation of VEGF as the leading cause of the positive effect of Netrin-1-carrying BMSCs in the revascularization of rat limb ischemia." (PMID 30359296, 2018).
liver disease (1 paper, 2022). "According to the recently described potential link between hepatic inflammation and liver disease progression through netrin-1, we found an upregulation of its receptor NEO1 in the liver from patients with T2D." (PMID 36297056, 2022).
low grade glioma (1 paper, 2025). A grade I or grade II glioma arising from the central nervous system. "More than 50% of the miRNAs strongly inhibited NTN1 in LGG (low-grade glioma) and BLCA." (PMID 41407823, 2025).